ANKLE1 (ankyrin repeat and LEM domain containing 1)
Description:
Structure-selective DNA endonuclease that specifically cleaves branched DNA. Processes chromatin bridges during cytokinesis by cleaving DNA, both priming TREX1-mediated resolution and directly resolving bridges. Proper processing of chromatin bridges prevents their breakage during cytokinesis, thereby reducing DNA damage, micronuclei formation, and the activation of immune responses such as the cGAS-STING pathway. Acts as a DNA tension sensor that resolves stretched chromatin bridges during cell division by cleaving mechanically stressed and supercoiled DNA. Its activity increases in response to mechanical stress and negative supercoiling, specifically cleaving both strands of negatively supercoiled DNA at higher stretching forces.
Synonyms: ANKRD41; LEM3; FLJ39369; LEMD6
Tractability: PROTAC: ubiquitination databases record sites on it.
Gene: Protein-coding gene on chromosome 19 (17,281,645 to 17,287,649, forward strand). Ensembl gene ENSG00000160117.
Subcellular location: Cytoplasm; Nucleus; Midbody
Subcellular location (Human Protein Atlas): Cytosol; Nucleoplasm
Gene Ontology:
Molecular function: cobalt ion binding; DNA endonuclease activity; endonuclease activity; magnesium ion binding; manganese ion binding; protein binding
Biological process: DNA damage response; protein export from nucleus; double-strand break repair via homologous recombination; nucleic acid metabolic process; resolution of meiotic recombination intermediates; negative regulation of mitotic recombination; regulation of lymphoid progenitor cell differentiation; regulation of myeloid progenitor cell differentiation
Cellular component: cytoplasm; cytosol; midbody; nucleoplasm; nucleus
Genetic constraint (gnomAD): Loss-of-function variants: 59 observed, 53.59 expected, observed/expected ratio (o/e) 1.1, 90% interval 0.89 to 1.37. The upper end of that interval is the gene's LOEUF score, 1.37, which puts it in group 5 of 6, group 1 being the genes least tolerant of losing a copy. Missense variants: 771 observed, 776.49 expected, observed/expected ratio (o/e) 0.99, 90% interval 0.94 to 1.05. Synonymous variants: 341 observed, 322.17 expected, observed/expected ratio (o/e) 1.06, 90% interval 0.97 to 1.16.
Homologues: Orthologues: chimpanzee ANKLE1 (93% identical), macaque ANKLE1 (90% identical), pig ANKLE1 (69% identical), dog ANKLE1 (59% identical), guinea pig ANKLE1 (54% identical), mouse Ankle1 (52% identical), rat Ankle1 (52% identical), tropical clawed frog ankle1 (39% identical), zebrafish zgc:85936 (39% identical). Paralogues in human: LEMD3 (17% identical), LEMD2 (9% identical).